ZC3H12D (zinc finger CCCH-type containing 12D)
Description:
May regulate cell growth likely by suppressing RB1 phosphorylation. May function as RNase and regulate the levels of target RNA species (Potential). In association with ZC3H12A enhances the degradation of interleukin IL-6 mRNA level in activated macrophages. Serve as a tumor suppressor in certain leukemia cells. Overexpression inhibits the G1 to S phase progression through suppression of RB1 phosphorylation.
Synonyms: C6orf95; MCPIP4; TFL; dJ281H8.1; p34
Tractability: PROTAC: its protein half-life has been measured.
Gene: Protein-coding gene on chromosome 6 (149,446,795 to 149,485,014, reverse strand). Ensembl gene ENSG00000178199.
Subcellular location: Cytoplasm, P-body; Cytoplasm (Isoform 1); Cytoplasm (Isoform 3); Nucleus
Subcellular location (Human Protein Atlas): Cytoplasmic bodies; Nucleoplasm
Gene Ontology:
Molecular function: protein binding; mRNA binding; RNA endonuclease activity; metal ion binding
Biological process: 3'-UTR-mediated mRNA destabilization
Cellular component: cytoplasmic ribonucleoprotein granule; nucleoplasm; P-body; nucleus; cytoplasm
Genetic constraint (gnomAD): Loss-of-function variants: 11 observed, 21.25 expected, observed/expected ratio (o/e) 0.52, 90% interval 0.32 to 0.86. The upper end of that interval is the gene's LOEUF score, 0.86, which puts it in group 3 of 6, group 1 being the genes least tolerant of losing a copy. Missense variants: 740 observed, 651.42 expected, observed/expected ratio (o/e) 1.14, 90% interval 1.07 to 1.21. Synonymous variants: 333 observed, 282.64 expected, observed/expected ratio (o/e) 1.18, 90% interval 1.08 to 1.29.
Homologues: Orthologues: chimpanzee ZC3H12D (98% identical), macaque ZC3H12D (94% identical), pig ZC3H12D (69% identical), dog ZC3H12D (66% identical), rat Zc3h12d (65% identical), mouse Zc3h12d (65% identical), guinea pig ZC3H12D (61% identical), Caenorhabditis elegans rege-1 (30% identical), Drosophila melanogaster Regnase-1 (30% identical), Caenorhabditis elegans Y24D9B.1 (17% identical), Caenorhabditis elegans Y51H4A.13 (17% identical), Drosophila melanogaster CG42360 (15% identical), and 1 more. Paralogues in human: ZC3H12C (42% identical), ZC3H12A (41% identical), ZC3H12B (40% identical), NYNRIN (23% identical), N4BP1 (21% identical), KHNYN (20% identical).
Diseases named in the same sentence as ZC3H12D in open-access papers:
ZC3H12D is named in the same sentence as 33 diseases in open-access papers, as found by Europe PMC text mining. Sharing a sentence is not in itself a finding about the gene and the disease. The quoted sentences say what the papers report.
endometrial cancer (2 papers, 2023 to 2025). Primary or metastatic malignant neoplasm involving the endometrium (mucous membrane that lines the endometrial cavity). "Also, ZC3H12D is demonstrated to be highly expressed in human endometrial carcinomas but not or only weakly expressed in normal tissues, and patients with endometrial cancer with high expression of ZC3H12D have a better prognosis." (PMID 39907408, 2025).
follicular lymphoma (2 papers, 2021). Follicular lymphoma is a form of non-Hodgkin lymphoma characterized by a proliferation of B cells whose nodular structure of follicular architecture is preserved. "Because ZC3H12D was recognized as a tumor suppressor gene in follicular lymphoma and lung cancer patients, the role of ZC3H12D in metastasis was further examined." (PMID 34135341, 2021).
lung adenocarcinoma (2 papers, 2023 to 2025). A carcinoma that arises from the lung and is characterized by the presence of malignant glandular epithelial cells. "Furthermore, ZC3H12D was shown to be specifically upregulated in lung adenocarcinoma (LUAD), and increased ZC3H12D expression is associated with the increase in B cells and a better prognosis of LUAD." (PMID 39907408, 2025).
lung carcinoma (2 papers, 2021). "The profiling indicates the highest fold change of mRNA for zinc finger (ZF) CCCH domain containing protein 12D (ZC3H12D), a putative tumor suppressor in lymphoma and lung cancer patients, in lung cells (GSE76235)." (PMID 34135341, 2021). "ZC3H12D might act as a tumor-suppressor gene by regulating cell growth in lymphoma and lung cancer." (PMID 34585646, 2021).
multiple sclerosis (2 papers, 2021 to 2023). A progressive autoimmune disorder affecting the central nervous system resulting in demyelination. "MCPIP4 (also named TFL; encoded by Zc3h12d)-deficient mice were healthy but exhibited excessive T-cell activation in a multiple sclerosis model." (PMID 34215755, 2021).
Abdominal obesity (1 paper, 2019). Excessive fat around the stomach and abdomen. "The top four CpGs that were found to be differentially methylated between individuals with and without abdominal obesity were located at the genes c13orf36, ZC3H12D, MYO9B, and KCNG3 in females; and JPH3, TCP11L1, and GRIK3 in males (one CpG had no annotated gene)." (PMID 31212707, 2019).
breast carcinoma (1 paper, 2025). "Our study revealed that the expression of the endonuclease ZC3H12D and the RNA helicase DDX5, two RBPs, was significantly repressed and increased in human breast cancer tissues, respectively." (PMID 41263459, 2025). "The expression of ZC3H12D and DDX5 was reduced and increased in human breast cancer tissues, respectively, and was closely related to the prognosis of breast cancer patients." (PMID 41263459, 2025). "The expression and prognostic value of RBPs ZC3H12D (zinc finger CCCH domain‐containing protein 12D) and DDX5 (DEAD box protein 5) in breast cancer were analyzed in public databases and tumor samples." (PMID 41263459, 2025). "We found that different subtypes of breast cancer, including luminal, HER2+, and triple‐negative breast cancer (TNBC), exhibited reduced ZC3H12D expression." (PMID 41263459, 2025).
breast tumor (1 paper, 2025). "Overexpression of DDX5 can attenuate ZC3H12D‐induced suppression of CCND1 mRNA in breast tumor cells." (PMID 41263459, 2025). "These computational findings indicated that ZC3H12D likely regulates the cell cycle signaling pathway by modulating cell cycle‐related gene expression in human breast tumor cells." (PMID 41263459, 2025). "We further verified the role of ZC3H12D in regulating breast tumor cell cycle progression by knocking down ZC3H12D in MDA‐MB‐468 and MCF7 cells via infection with an shRNA‐expressing lentivirus." (PMID 41263459, 2025). "Overall, our results strongly indicate that ZC3H12D regulates the cell cycle signaling pathway and induces G1/S arrest in breast tumor cells." (PMID 41263459, 2025). "To determine the function of ZC3H12D in breast tumor cell cycle progression, we measured the cell cycle distribution via flow cytometry." (PMID 41263459, 2025). "Although ZC3H12D expression was already lower in breast tumor cells, further knockdown of ZC3H12D significantly increased the mRNA expression of cell cycle‐promoting genes, including CCND1." (PMID 41263459, 2025). "To date, the role and mechanism of ZC3H12D in human cancer progression, especially in regulating the cell cycle progression of breast tumor cells, are still unknown." (PMID 41263459, 2025). "Next, we explored the roles of DDX5 and ZC3H12D in breast tumor progression." (PMID 41263459, 2025). "The high expression of the CCND1 mRNA in breast tumor cells led us to look for potential RBPs that could compensate for the degradation by ZC3H12D." (PMID 41263459, 2025). "The functions of ZC3H12D and DDX5 in breast tumor cell cycle regulation and tumor progression were determined in vitro and in vivo." (PMID 41263459, 2025). "In conclusion, our findings established that ZC3H12D and DDX5 play distinct anticancer and carcinogenic roles by modulating cell cycle progression in breast tumors." (PMID 41263459, 2025). "Ribosomal protein L4 (RPL4) was shown to interact with ZC3H12D and facilitate the degradation of the CCND1 mRNA in breast tumor cells." (PMID 41263459, 2025). "Overall, we unveiled a novel regulatory network in which ZC3H12D and DDX5 antagonistically regulate the mRNA stability and expression of cell cycle‐promoting genes in breast tumor cells." (PMID 41263459, 2025). "In this study, we discovered that the RBPs ZC3H12D and DDX5 (DEAD‐box helicase 5) antagonistically regulate CCND1 mRNA stability and expression in breast tumor cells." (PMID 41263459, 2025). "Therefore, we proposed a model to elucidate the potential antagonistic roles of ZC3H12D and DDX5 in regulating the cell cycle progression of breast tumor cells." (PMID 41263459, 2025). "ZC3H12D degraded the mRNAs of CCND1 and other cell cycle‐promoting genes by binding to the conserved stem–loop structure localized in the 3′UTR via its RNase domain, thereby inhibiting their expression and the G1/S phase transition of breast tumor cells." (PMID 41263459, 2025). "In addition, DDX5 and ZC3H12D were also positively and negatively correlated with the expression of several cell cycle‐promoting genes, such as WEE1 and CDK2, in human breast tumor tissues." (PMID 41263459, 2025). "Notably, DDX5 and ZC3H12D could positively and negatively regulate the expression of CCND1, respectively, in human breast tumors." (PMID 41263459, 2025).
colorectal cancer (1 paper, 2022). A primary or metastatic malignant neoplasm that affects the colon or rectum. "Obviously, high expression of the four genes (DDX56, CTSL, ZC3H12D, and PSMC5) could promote the expression of PD-L1 as they have been proven to be promising biomarkers and immunotherapy targets in a variety of tumors, including colorectal cancer, NSCLC, and gastric cancer." (PMID 35647031, 2022).
depression (1 paper, 2025). "We discovered that the five key genes CYP4F2, KCNA3, KISS1R, LILRA5 and ZC3H12D remained different after Venn diagram overlap of DEGs across depression and renal failure datasets." (PMID 40595897, 2025). "Further, protein-protein interaction (PPI) network analysis pinpointed five central genes CYP4F2, KCNA3, KISS1R, LILRA5, and ZC3H12D as pivotal players in the shared pathophysiology of depression and renal failure." (PMID 40595897, 2025). "PPI network analysis identified 23 hub genes, including CYP4F2, KCNA3, KISS1R, LILRA5, and ZC3H12D, as key players in the shared pathophysiology of ESRD and depression." (PMID 40595897, 2025). "PPI network analysis identified CYP4F2, KCNA3, KISS1R, LILRA5, and ZC3H12D as key players in the shared pathophysiology of ESRD and depression." (PMID 40595897, 2025).
tongue cancer (1 paper, 2021). A malignant neoplasm affecting the tongue. "Previous studies have reported that the expression of LEPR 42, PFKM 43, 44, PGK1 45, 46, CYP19A1 47, 48, SLC20A1 49, and ZC3H12D 50 were associated with tumorigenesis and progression in various tumor types, which support the further identification and exploring in tongue cancer." (PMID 33758601, 2021). "In our study, we also found aberrant down-regulation of ZC3H12D in tongue cancer patients with better prognosis." (PMID 33758601, 2021). "PGK1, SLC20A1, LEPR, CYP19A1, ZC3H12D, and PFKM were found to be independent predictors in tongue cancer." (PMID 33758601, 2021).
tumor (10 papers, 2008 to 2025). "Recent report showed that overexpression of Zc3h12D (also designated as p34) exerts tumor suppressor function and an A/G SNP of Zc3h12D was associated with lung cancer." (PMID 18682727, 2008). "This tumor-mediated change in the ZC3H12D localization pattern was further confirmed using two other anti-ZC3H12D antibodies." (PMID 34135341, 2021). "Zc3h12d expression in leukocytes derived from tumor-bearing mice was enhanced by tumor-bearing lungs in a coculture system in vitro." (PMID 34135341, 2021). "ZC3H12D was previously considered a potential tumor suppressor." (PMID 41263459, 2025). "Here, we investigated the role played by the ZC3H12D gene in HNSCC and how it affects tumor immune infiltration." (PMID 39907408, 2025).
cancer (5 papers, 2008 to 2025). A tumor composed of atypical neoplastic, often pleomorphic cells that invade other tissues. "In addition, downregulation of ZC3H12D expression promotes the proliferation of osteosarcoma cells, indicating the anticancer potential of ZC3H12D in different human cancers." (PMID 41263459, 2025). "In addition to the immune-related pathways, we also found that the co-expressed genes of ZC3H12D expression were enriched in well-known cancer-related pathways, such as NF-kB signaling pathway, which needed to validate its function in cancer in the further." (PMID 35090416, 2022). "Considering NF-κB signaling is over-activated in most of cancer, it would be extremely interesting to observe whether Zc3h12D is also a negative regulator of NF-κB signaling." (PMID 18682727, 2008).
ZC3H12D also shares sentences with these, for which no sentence is quoted: hepatocellular carcinoma (2 papers); infection (2); lymphoma (2); autoimmune disease (1); B-cell lymphoma (1); B-cell neoplasm (1); Burkitt lymphoma (1); chronic hepatitis B (1); chronic lymphocytic leukemia (1); diffuse large B-cell lymphoma (1); gastric cancer (1); head and neck squamous cell carcinoma (1); hemophagocytic lymphohistiocytosis (1); Hodgkins lymphoma (1); leukemia (1); leukoaraiosis (1); lymphoid neoplasm (1); malaria (1); renal failure (1); Waldenstrom macroglobulinemia (1).